QRICH1 (glutamine rich 1)
Diseases named in the same sentence as QRICH1 in open-access papers:
QRICH1 is named in the same sentence as 34 diseases in open-access papers, as found by Europe PMC text mining. Sharing a sentence is not in itself a finding about the gene and the disease. The quoted sentences say what the papers report.
depression (2 papers, 2024 to 2025). "In previous GWAS and clinical studies, these genes have been associated with neurogenesis (WNT3), neurodevelopmental delays (QRICH1), addiction (HCG27), depression (CCDC71, CYP21A2), and other brain-related disorders." (PMID 39269986, 2024).
necrotizing enterocolitis (2 papers, 2023 to 2024). Necrotizing enterocolitis (NEC) is a devastating disease that affects mostly the intestine of premature infants. "The PERK-eIF2ɑ axis is responsible for regulating QRICH1 in necrotizing enterocolitis, combined with our research, there may be a complex network of loops involved in the regulation of QRICH1." (PMID 39227586, 2024). "Endoplasmic reticulum (ER) stress plays a critical role in necrotizing enterocolitis (NEC) pathogenesis through the PERK-eIF2ɑ-QRICH1 axis." (PMID 38129421, 2023).
B-cell neoplasm (1 paper, 2024). A group of heterogeneous lymphoid tumors generally expressing one or more B-cell antigens or representing malignant transformations of B-lymphocytes. "QRICH1 gene mutations were mainly detected in mature B-cell neoplasms, endometrial cancers and melanomas." (PMID 39227586, 2024).
breast carcinoma (1 paper, 2021). "Our results indicated that SF1, TRA2B, and THRAP3 were the top 3 stably expressed RGs in breast cancer tissues and that THRAP3, RHOA, and QRICH1 were the top 3 stably expressed RGs in breast cancer cell lines." (PMID 34895237, 2021). "Our results show that RG combinations SF1 + TRA2B + THRAP3 and THRAP3 + RHOA + QRICH1 showed stable expression in breast cancer tissues and cell lines, respectively, and that they displayed good interchangeability." (PMID 34895237, 2021). "Therefore, we considered the multi-RG combination SF1 + TRA2B + THRAP3 + RHOA + QRICH1 as the most promising choice for breast cancer research (both in breast cancer tissues and cell lines)." (PMID 34895237, 2021). "Therefore, we recommend that SF1 + TRA2B + THRAP3 and THRAP3 + RHOA + QRICH1 be adopted as the RG combinations for breast cancer tissue and cell line research, respectively." (PMID 34895237, 2021). "The Ct values varied from 16.35 (RPL13A) to 24.57 (QRICH1) across various breast cancer tissues." (PMID 34895237, 2021). "In the breast cancer cell group THRAP3, RHOA, and QRICH1 were the top three stably expressed genes, while B2M, TUBA1A, and ACTB were the least stably expressed genes." (PMID 34895237, 2021). "For all breast cancer tissue and cell line samples, THRAP3, RHOA, QRICH1 were the most stably expressed genes, and TUBA1A, B2M, ACTB were the least stably expressed RGs." (PMID 34895237, 2021). "In the breast cancer cell line group, THRAP3, RHOA, and QRICH1 were the three most stably expressed genes, while B2M, ACTB, and TUBA1A were the least stably expressed genes." (PMID 34895237, 2021). "There was a high correlation (R2 from 0.815 to 0.979 in breast cancer tissues, and R2 from 0.927 to 0.995 in breast cancer cell lines) between stable RGs and SF1 + TRA2B + THRAP3 + RHOA + QRICH1." (PMID 34895237, 2021). "There was also a moderate-to-high correlation (R2 from 0.621 to 0.709 in breast cancer tissues, and R2 from 0.600 to 0.916 in breast cancer cell lines) between unstable RGs and SF1 + TRA2B + THRAP3 + RHOA + QRICH1." (PMID 34895237, 2021). "The top three genes for breast cancer tissues and cell lines were SF1 + TRA2B + THRAP3 and THRAP3 + RHOA + QRICH1, respectively, and therefore a total of 5 RGs (SF1, TRA2B, THRAP3, RHOA, QRICH1) should be considered." (PMID 34895237, 2021). "In the case of studies including both breast cancer tissue and cell line research, the THRAP3 + RHOA + QRICH1 combination would be optimal." (PMID 34895237, 2021). "In the breast cancer cell lines, THRAP3, RHOA, and QRICH1 were the most stably expressed RGs." (PMID 34895237, 2021). "In breast cancer cell lines, when the optimal RG combinations SF1 + TRA2B + THRAP3 + RHOA + QRICH1, SF1 + TRA2B + THRAP3, or THRAP3 + RHOA + QRICH1 were used for normalization, the expression of FAAH was highest in MCF-7 cells, followed by MCF-10A cells, and was least in MDA-MB-231 cells." (PMID 34895237, 2021). "Therefore, to confirm the roles of these genes on the vital regulatory mechanisms in breast cancer, we compared the potential role of novel RGs (SF1, TRA2B, THRAP3, RHOA, and QRICH1) vs. traditional RGs (ACTB, and GAPDH) in the normalization of target gene expression." (PMID 34895237, 2021).
cardiac hypertrophy (1 paper, 2025). "Then, QRICH1 may be a new diagnostic and therapeutic approach for pathological cardiac hypertrophy and hypertrophy-induced heart failure." (PMID 40355839, 2025). "Compared with corresponding parameters in control mice, QRICH1 KD mice also exhibited blunted myocardial hypertrophy, remodeling and inflammatory response." (PMID 40355839, 2025). "Collectively, these data suggest that cardiomyocyte-specific knockdown of QRICH1 can prevent the occurrence of pathological cardiac hypertrophy." (PMID 40355839, 2025). "In conclusion, our study demonstrates that QRICH1 affects the progression of pathological cardiac hypertrophy by regulating the transcription of ATF6." (PMID 40355839, 2025). "Although the precise timing of QRICH1 activation in pathological cardiac hypertrophy remains elusive, the concurrent increase of ANP suggests that the activation of cardiac myocyte QRICH1 is dependent on the stress conditions of heart failure." (PMID 40355839, 2025). "To confirm the protective role of QRICH1 against cardiac hypertrophy, we employed an alternative model of pathological myocardial hypertrophy induced by ISO injection." (PMID 40355839, 2025). "Taken together, these data suggest that QRICH1 exacerbates stress-induced pathological cardiac hypertrophy, potentially through the activation of the mTOR signaling pathway and its interaction with ATF6." (PMID 40355839, 2025). "This interaction suggests that QRICH1 may play a role in regulating the pathogenesis of myocardial hypertrophy." (PMID 40355839, 2025). "Accordingly, we speculated that QRICH1 influences the occurrence and development of cardiac hypertrophy by regulating ATF6." (PMID 40355839, 2025). "To confirm that the effect of QRICH1 promoting cardiac hypertrophy in vivo is due to the activation of ATF6 in cardiomyocytes under growth stimuli, we used dual AAV9 injections to evaluate the effects of ATF6 overexpression on cardiac phenotypes in QRICH1 KD mice." (PMID 40355839, 2025). "To assess the functional impact in this context, we employed gain- and loss-of-function approaches, using AAV9 injections to establish cardiac-specific QRICH1 knockdown or overexpression models in transverse aortic constriction (TAC) or isoproterenol (ISO)-induced cardiac hypertrophy." (PMID 40355839, 2025). "In this study, we explored the role of QRICH1 in pathological cardiac hypertrophy." (PMID 40355839, 2025). "Our current findings demonstrate that QRICH1 may act as a significant regulator in managing pathological cardiac hypertrophy." (PMID 40355839, 2025). "In this study, we confirmed that QRICH1 could exacerbate hypertrophy, fibrosis, apoptosis, inflammation, and cardiac dysfunction in cardiac hypertrophy models." (PMID 40355839, 2025). "Next, we sought to determine whether QRICH1 overexpression in the heart could exacerbates TAC myocardial hypertrophy." (PMID 40355839, 2025). "We further investigated whether QRICH1 could regulate the progression of cardiac hypertrophy in cardiomyocytes." (PMID 40355839, 2025). "Hence, the beneficial effects of QRICH1 suppression on cardiac hypertrophy were reversed by ATF6 overexpression under growth stimuli." (PMID 40355839, 2025). "However, overexpression of QRICH1 exacerbated cardiac hypertrophy, remodeling, dysfunction, cell apoptosis, and inflammatory responses." (PMID 40355839, 2025). "To investigate the potential impact of QRICH1 on the development of cardiac hypertrophy and heart failure, we initially analyzed the expression levels of QRICH1 in left ventricle samples from patients with left ventricular hypertrophy (LVH) compared to normal donor heart samples." (PMID 40355839, 2025). "To identify potential target promoters that could influence cardiac hypertrophy, we compared the transcriptomes from WT versus QRICH1 KD cells after ISO treatment and identified 4063 differentially expressed genes (DEGs), with 1862 increased and 2201 decreased genes in KD cells." (PMID 40355839, 2025).
cardiac hypertrophy (continued). "We aimed to investigate whether QRICH1 contributes to cardiac hypertrophy." (PMID 40355839, 2025). "We found that both QRICH1 mRNA and protein levels were significantly increased in LVH samples, indicating that elevated QRICH1 expression may be associated with the development of cardiac hypertrophy and failure." (PMID 40355839, 2025). "To test whether QRICH1 is responsive to pathological cardiac hypertrophy, we conducted a study using a mouse model subjected to pressure overload induced by transverse aortic constriction (TAC) and a catecholamine-induced model injected with isoproterenol (ISO)." (PMID 40355839, 2025). "In addition to its role in maintaining cellular protein homeostasis, QRICH1 plays a critical role under pathological conditions such as inflammatory or metabolic diseases, suggesting its involvement in various cardiovascular diseases, including pathological cardiac hypertrophy." (PMID 40355839, 2025). "In response to ISO, in QRICH1 KD mice, overexpression of ATF6 reactivated the mTOR signaling pathway, resulting in exacerbated cardiac hypertrophy and dysfunction." (PMID 40355839, 2025). "QRICH1 plays a pivotal role in cardiac hypertrophy by regulating ATF6, and QRICH1 may be a potential new therapeutic target for pathological cardiac hypertrophy." (PMID 40355839, 2025). "Therefore, QRICH1 may play a pivotal role in orchestrating protein synthesis and folding, as well as sustaining protein homeostasis, by modulating the transcription of ATF6 during cardiac hypertrophy." (PMID 40355839, 2025).
congenital heart disease (1 paper, 2025). A heart disease that is present at birth. "Variants in QRICH1 have been associated with developmental delay, neurodevelopmental disorders, renal agenesis, and congenital heart disease, underscoring its importance in maintaining the normal structure of tissues with high protein synthesis demands." (PMID 40355839, 2025).
heart failure (1 paper, 2025). Inability of the heart to pump blood at an adequate rate to meet tissue metabolic requirements. "This approach aims to elucidate QRICH1's role at various stages from compensation to decompensation and potentially heart failure, thus providing insights into therapeutic interventions." (PMID 40355839, 2025).
left ventricular hypertrophy (1 paper, 2025). Enlargement of the LEFT VENTRICLE of the heart. "We observed an increased expression of QRICH1 in the hearts of humans and mice with left ventricular hypertrophy (LVH)." (PMID 40355839, 2025).
leukemia (1 paper, 2024). A malignant (clonal) hematologic disorder, involving hematopoietic stem cells and characterized by the presence of primitive or atypical myeloid or lymphoid cells in the bone marrow and the blood. "Overall, we have proved that QRICH1 overexpression suppressed leukemia cell infiltration and proliferation in vivo." (PMID 39227586, 2024). "Significant infiltrations of leukemia cells in the bone marrow, spleen, and liver of T-ALL mice positive controls (Vector1 group) than those overexpressing QRICH1 suggested the protective effect of QRICH1 on T-ALL in vivo." (PMID 39227586, 2024).
melanoma (1 paper, 2024). A malignant, usually aggressive tumor composed of atypical, neoplastic melanocytes. "In the GSE78220 dataset with 28 melanoma patients, the expression level of QRICH1 before PD-1 treatment was significantly lower in the complete response group compared to the partial response and progressive disease groups, supporting the immunomodulatory role of QRICHI in the tumor immunity." (PMID 39227586, 2024).
mental retardation (1 paper, 2011). "The other genes are potassium channel tetramerization domain containing 1 (KCTD1), zinc finger, myeloproliferative and mental retardation type 2 (ZMYM2)/zinc finger protein 198 (ZNF198), ZMYM3/ZNF261, ZMYM4/ZNF262 and glutamine-rich protein 1 (QRICH1)." (PMID 22011512, 2011).
Myocardial fibrosis (1 paper, 2025). "In our study, we utilized tissue-specific AAV9 virus transfection to knock down QRICH1 in cardiomyocytes, which delayed myocardial fibrosis, reduced apoptosis, and improved myocardial remodeling in a mouse model of pathological hypertrophy." (PMID 40355839, 2025).
polymicrogyria (1 paper, 2023). A developmental brain abnormality characterized by an excessive amount of small convolutions on the surface of the brain and cognitive dysfunction. "Thus, we report parietal predominant polymicrogyria as a phenotype associated with QRICH1 variants." (PMID 37486637, 2023). "In addition to detecting pathogenic variants in genes previously linked to polymicrogyria (eg, ADGRG1/GPR56, SCN3A, TUBB2B), we discovered 6 genes linked to polymicrogyria for the first time (QRICH1, TMEM161B, PANX1, KIF26A, SCN2A, and MAN2C1)." (PMID 37486637, 2023).
T-cell prolymphocytic leukemia (1 paper, 2024). A slow-growing type of leukemia (blood cancer) in which too many lymphocytes are found in the bone marrow and/or blood. "In the GSE72623 and GSE147930 datasets, QRICH1 was consistently downregulated in adult T-cell prolymphocytic leukemia (T-PLL) and pediatric T-ALL." (PMID 39227586, 2024).
tumor (2 papers, 2024 to 2025). "Co-overexpression of GRP78 in QRICH1 partially reversed the regulatory effects of QRICHI on the proliferation and apoptosis of T-ALL cells, validating that GRP78 was essential for the anti-tumor role of QRICH1." (PMID 39227586, 2024). "Future studies are needed to illustrate the role of QRICH1 in the tumor immunity of pediatric T-ALL." (PMID 39227586, 2024). "Considering the role of GRP78 in favoring the pro-tumor immunity, we further explored the immunomodulatory functions of QRICH1." (PMID 39227586, 2024). "Collectively, we for the first time identified that QRICH1 may be a tumor-suppressor gene that predicted the prognosis of pediatric T-ALL." (PMID 39227586, 2024). "We hypothesize that the expression patterns of QRICH1 and VAMP8 contribute to defining the trajectory trail for MSig GBM subtypes, offering insights into the tumour's evolutionary driving forces." (PMID 41292185, 2025).
cancer (1 paper, 2024). A tumor composed of atypical neoplastic, often pleomorphic cells that invade other tissues. "We further searched QRICH1 gene mutations in the TCGA Pan-Cancer Atlas, and missense mutations were predominant." (PMID 39227586, 2024). "Interestingly, shallow deletion was dominant in the mRNA expression of QRICH1 in almost all types of cancers." (PMID 39227586, 2024). "In our study, a persistent induction of Tm upregulated QRICH1 and increased cell death, suggesting that Tm may promote cancer cell death by activating QRICH1." (PMID 39227586, 2024).
neurodevelopmental disorder (1 paper, 2025). A behavioral and cognitive disorder with onset during the developmental period that involves impaired or aberrant development of intellectual, motor, or social functions. "In humans, variants of QRICH1 can lead to developmental defects, abnormal longitudinal bone formation, or neurodevelopmental disorders." (PMID 40355839, 2025).
QRICH1 also shares sentences with these, for which no sentence is quoted: Ververi-Brady syndrome (2 papers); 3-M syndrome (1); acromelic dysplasia (1); brain disease (1); cardiovascular diseases (1); Cerebellofaciodental Syndrome (1); developmental and epileptic encephalopathy (1); developmental delay (1); endometrial cancer (1); Floating-Harbor syndrome (1); hypertrophy (1); metabolic disease (1); Mowat-Wilson syndrome (1); Neurodevelopmental delay (1); renal agenesis (1); T-cell acute lymphoblastic leukemia (1); X-linked mental retardation syndrome (1).